CCL4 (C-C motif chemokine ligand 4)
Diseases named in the same sentence as CCL4 in open-access papers (continued):
Sharing a sentence is not in itself a finding about the gene and the disease.
chordoma (1 paper, 2010). Chordomas are rare malignant tumors arising from embryonic remnants of the notochord in axial skeleton. "We analyzed gene expression patterns and genomic copy number variations in five putative chordoma cell lines (U-CH1, CCL3, CCL4, GB60, and CM319)." (PMID 21253487, 2010). "At a minimum, because all chordomas previously analyzed by array CGH harbored multiple copy number abnormalities, the lack of copy number aberrations indicates that GB60 and CCL4 are unlikely to be chordoma tumor cells." (PMID 21253487, 2010). "Our analyses revealed that CCL3, CCL4, and GB60 are not chordoma cell lines, and that CM319 is a cancer cell line possibly derived from chordoma, but lacking expression of key chordoma biomarkers." (PMID 21253487, 2010). "CCL4 and GB60 may indeed be derived from cell populations contained in a chordoma tumor, but are most likely not neoplastic chordoma cells." (PMID 21253487, 2010).
chronic heart failure (1 paper, 2021). "Patients with chronic heart failure and MDD have elevated peripheral MIP-1β/CCL4 levels and this is more pronounced in patients with severe depression." (PMID 34226490, 2021).
chronic liver failure (1 paper, 2024). Liver failure that develops slowly and gradually for some time, possibly for years, often as the result of cirrhosis, or malnutrition. "Similarly to our present investigation, Broermann, Schmid discovered that anti-fibrotic effects caused by the PDE5 inhibitor are represented by differently expressed miRNAs in the liver and reduce CCL4-induced chronic liver failure in rats." (PMID 38413963, 2024).
cleft lip (1 paper, 2025). Congenital defect in the upper lip where the maxillary prominence fails to merge with the merged medial nasal prominences. "IHC findings showed decreased MSX1, NFκB p65, and CCL4 proteins in cleft lip connective tissue and endothelium, while RYK protein was decreased only in cleft connective tissue." (PMID 41226636, 2025). "This indicates that the decrease in MSX1, NFκB p65, and CCL4 proteins might be involved in postnatal cleft lip morphopathogenesis, while the exact mechanisms are relatively unclear." (PMID 41226636, 2025). "Although the presence of orofacial clefts is associated with increased pro-inflammatory cytokines and the presence of inflammation in oral mucosa, our study results suggest that NFκB p65 and CCL4-positive cells in cleft lip tissue were decreased in comparison to control tissue, which was unexpected." (PMID 41226636, 2025). "This most likely also affected the presence of NFκB p65 and CCL4 proteins in cleft lip tissue." (PMID 41226636, 2025). "Immunohistochemistry (IHC) for MSX1, RYK, NFκB p65, and CCL4 proteins and chromogenic in situ hybridization (CISH) for MSX2, RYK, and PTX3 genes were used to analyze postnatal human cleft lip tissue (15 patients) and control tissue (6 patients)." (PMID 41226636, 2025). "The information gathered in this study has provided additional insight about the presence and distribution of MSX1, RYK, NFκB p65, and CCL4 proteins and MSX2, RYK, and PTX3 genes in human cleft lip tissue." (PMID 41226636, 2025). "In cleft lip patients, most statistically significant positive correlations involved the following factors: the PTX3 gene and NFκB p65 protein, then MSX1 protein-positive cells, RYK protein-positive cells, the CCL4 protein, the RYK gene, and then MSX2 gene-signal-containing cells." (PMID 41226636, 2025). "The only statistically negative correlation seen in the cleft lip patient group was identified between the MSX2 gene in connective tissue (CISH) and the CCL4 protein in the endothelium (IHC), which was not present in the control group." (PMID 41226636, 2025). "The lack of statistically significant difference in NFκB p65 and CCL4-positive epithelial cells between controls and cleft lip patients might indicate that the surface epithelium most likely is not directly connected with postnatal changes that affect cleft lip tissue homeostasis." (PMID 41226636, 2025).
colorectal adenocarcinoma (1 paper, 2024). The most common type of colorectal carcinoma. "However, loss‐of‐function RNF45 mutations reduce CC chemokine ligand (CCL4) levels and prevent CD8+ T cell infiltrations, leading to noninflamed TME in high‐frequency microsatellite instability colorectal adenocarcinomas." (PMID 37974379, 2024).
cryptococcosis (1 paper, 2023). An acute or chronic, localized or disseminated infection by Cryptococcus neoformans. "Although CCL4 is increased in the lungs of various animal models and in the human cerebrospinal fluid in response to C. neoformans infection, the role of this chemokine in cryptococcosis is still not well understood and appears not to be as critical as CCL2." (PMID 38033163, 2023).
Cryptosporidium infection (1 paper, 2022). "STAg-treated mice also had a lower abundance of Ccl4, the prostaglandin receptor Ptger3, and granzymes B and K, which have all previously been implicated in Cryptosporidium infection." (PMID 34928716, 2022).
cutaneous leishmaniasis (1 paper, 2024). Leishmaniasis affecting the skin. "To determine if CCR5 was associated with more severe disease in mice, we evaluated Ccl3, Ccl4, and Ccr5 gene expression in lesions from two murine models of severe disease in murine cutaneous leishmaniasis." (PMID 38709823, 2024).
cyst (1 paper, 2022). A sac-like closed membranous structure that may be empty or contain fluid or amorphous material. "The chemokine profile is different compared to trophozoites, the main up-regulated chemokines are the same, but CCL4, CCL4L2, CSF1, CCL5, CXCL5, and CX3CL1 are more highly up-regulated in the cyst interaction." (PMID 35573800, 2022).
cytomegalovirus infection (1 paper, 2010). A herpesvirus infection caused by Cytomegalovirus. "In murine cytomegalovirus infection and in Toxoplasma gondii infection, early release of CCL3 and CCL4 from APCs is vital for the influx of NK cells into affected tissues, and these cells are an important source of IFN-γ, which induces macrophages and dendritic cells to secrete CXCL9 and CXCL10." (PMID 20828409, 2010).
demyelinating disease (1 paper, 2023). A broad group of disorders that affect the myelin sheaths that cover the neurons. "Similarly, CCL3 and CCL4 have been shown to contribute to demyelinating disease." (PMID 37496672, 2023).
eating disorder (1 paper, 2022). A broad group of psychological disorders with abnormal eating behaviors leading to physiological effects from overeating or insufficient food intake. "In a cross-sectional study, however, individuals with AN (n = 56) had lower blood CCL4 concentrations as HC (n = 51), and CCL4 levels correlated negatively with BMI and eating disorder psychopathology." (PMID 36226111, 2022).
enterovirus infection (1 paper, 2020). "In contrast, in the infants with enterovirus infection increased levels of CXCL10 (IP-10), which is related to Th1 immunity and IL-17 were found after the infection, while CCL4 (MIP-1β) and CCL22 (MDC), remained decreased after enterovirus infection." (PMID 33643278, 2020).
eosinophilic esophagitis (1 paper, 2016). Eosinophilic esophagitis (EoE) is a chronic, allergic disease of the esophagus characterized clinically by symptoms of esophageal dysfunction (including vomiting, dysphagia, feeding disorders, food impaction and abdominal pain) which persist after treatment with proton pump inhibitors (PPIs). "Besides, IL-13 has been implicated in inflammation and remodeling by inducing chemokines (CCL-3, CCL-4, CCL-5 and CXCL-1), and IL-13 is a direct inducer of both CCL11 and CCL24 in eosinophilic esophagitis." (PMID 27533463, 2016).
Focal cortical dysplasia (1 paper, 2019). A type of malformation of cortical development that primarily affects areas of neocortex. "Lastly, miR-195-5p downregulation has been shown to dysregulate the function of the chemokine CCL4 associated with inflammation in the etiology of focal cortical dysplasia." (PMID 31861723, 2019).
glomerulopathy (1 paper, 2015). "For instance, as recently reviewed, the chemokines CCL2, CCL3, and CCL4 correlate with the severity of S. mansoni, where CCL3 is related to the recruitment of eosinophils and induction of granulomatous pathology, while CCL2 is associated with glomerulopathy." (PMID 26082781, 2015).
growth disorders (1 paper, 2021). "The brain-to-body weight ratio decreased significantly (p < 0.0001) in the CCL4 treatment group, showing this group′s metabolic or growth disorders." (PMID 34946608, 2021).
haemolytic anaemia (1 paper, 2025). "CXCL13 has been proposed as a potential biomarker of activity in SLE and LN, and CXCL13 and CCL4 were shown to have utility in SLE-related haemolytic anaemia, while their roles in NPSLE remain elusive." (PMID 40672966, 2025).
hairy cell leukemia (1 paper, 2015). Hairy cell leukemia (HCL) is a rare type of leukemia in which abnormal B-lymphocytes are present in the bone marrow, spleen and peripheral blood. "Similar inhibitory effects on proliferation and survival, CCL3/CCL4 secretion, and CXCL12 signaling occur in hairy cell leukemia (HCL) treated with ibrutinib." (PMID 26022368, 2015).
Headache (1 paper, 2023). Cephalgia, or pain sensed in various parts of the head, not confined to the area of distribution of any nerve. "We selected the genes CCL4 and IL7R, which are regulatory T-cell-associated markers, for local AE and headache, respectively." (PMID 38022684, 2023). "The genes CCL4 and IL7R were associated with local AE and headache, respectively." (PMID 38022684, 2023).
Hyperkeratosis (1 paper, 2023). Hyperkeratosis is a histopathological term defining a thickened stratum corneum and may be present in many different skin conditions, with many possible overlaps. "We observed a significant increase in inflammatory factors (such as TNF-α, IL-1β, CXCL1, CXCL2, CCL4, and TLR7) and exacerbates hyperkeratosis and keratosis in STAT3 mice." (PMID 37465147, 2023).
hyperplastic polyp (1 paper, 2024). A polyp found mainly in the stomach and colon. "However, CCL4 (p = 0.052) and CCL19 (p = 0.088) expression in lesions tended to be lower in hyperplastic polyps." (PMID 38338661, 2024).
hypertriglyceridemia (1 paper, 2015). A laboratory test result indicating elevated triglyceride concentration in the blood. "Hypertriglyceridemia was associated with increased levels of CCL4, which contributes to the migration of Gr1low monocytes." (PMID 26344769, 2015). "Hypertriglyceridemia was accompanied by an increased expression of tissue, and plasma CCL4 and blood Gr1low monocyte depletion involved a pertussis-toxin-sensitive receptor axis." (PMID 26344769, 2015). "We identified CCL4 as one of the potential molecules mediating the changes in the distribution of blood monocytes during hypertriglyceridemia." (PMID 26344769, 2015).
idiopathic inflammatory myopathies (1 paper, 2022). "Increased serum levels of CCL4 were observed in patients with idiopathic inflammatory myopathies." (PMID 36570445, 2022).
ileitis (1 paper, 2024). "Other factors that were only increased in the BALF of SHIP-1−/− mice with ileitis were IL-33 and TNFα, while IL-6, CCL2, and CCL4 were more significantly increased in the lungs of SHIP-1−/− mice with ileitis." (PMID 39432107, 2024). "Other differences in circulating cytokines were also noted including increases in IL-5, CCL3 and CCL4 that were not seen in SHIP-1−/− without ileitis." (PMID 39432107, 2024).
interstitial pulmonary disease (1 paper, 2021). "According to articles that assess the interstitial pulmonary disease, pulmonary sepsis, or oxidant lung damage animal models, CCL4 (MIP-β) exerts an important part in the disease pathogenic mechanism and respiratory tract defenses." (PMID 34054345, 2021).
intracranial hypertension (1 paper, 2024). A finding characterized by increased cerebrospinal fluid pressure within the skull. "On the basis of these results, we used CSF and serum from patients with intracranial hypertension for control and showed that CCL4 was significantly higher in both the inflammatory and tumor groups than in the control group." (PMID 39364412, 2024).
intraepithelial neoplasia (1 paper, 2025). A precancerous neoplastic process that affects the squamous, glandular, or transitional cell epithelium without evidence of invasion. "Accordingly, MIP-1β/CCL4 expressions were higher in lesions from patients with PCa and with intraepithelial neoplasia (PIN) lesions than in nonneoplastic prostate patients, but to our knowledge, no reports are available regarding MIP-1β/CCL4 plasma levels in PCa patients." (PMID 40427694, 2025).
ischemia (1 paper, 2020). A hypoperfusion of the BLOOD through an organ or tissue caused by a PATHOLOGIC CONSTRICTION or obstruction of its BLOOD VESSELS, or an absence of BLOOD CIRCULATION. "In recent years, evidences support that MSC-derived EVs play therapeutic roles in several kinds of liver damage induced by CCL4, D-GalN/LPS, hepatic ischemia reperfusion, and hepatic S100." (PMID 31918749, 2020).
keloid (1 paper, 2023). An irregularly shaped, elevated mark on the skin caused by deposits of excessive amounts of collagen during wound healing. "Additionally, CCL3, CCL4, G-CSF, and GM-CSF levels were significantly elevated in the plasma of keloid patients compared to healthy controls, implicating inflammatory cytokines in the formation of keloid lesions." (PMID 37524866, 2023).
low grade glioma (1 paper, 2024). A grade I or grade II glioma arising from the central nervous system. "In low-grade gliomas (LGG), CCL4 is a key element for the survival of LGG stem cells." (PMID 39364412, 2024).
lupus nephritis (1 paper, 2018). Glomerulonephritis in the context of systemic lupus erythematosus. "We found that CKD-506 significantly decreased levels of IFN-γ, IL-1β, IL-4, IL-6, IP-10, MCP-1, and CCL4 in the kidney extracts of mice with lupus nephritis." (PMID 30470828, 2018).
Lyme disease (1 paper, 2010). Lyme disease (named after the towns in the USA where the disease was first identified) is a bacterial infection caused by Borrelia burgdorferi. "B. burgdorferi activates monocytes/macrophages directly to secrete a number of chemokines, including CCL4, which are important in innate immune responses both early and late in Lyme disease." (PMID 20828409, 2010).
mantle cell lymphoma (1 paper, 2013). Mantle cell lymphoma is a rare form of malignant non-Hodgkin lymphoma affecting B lymphocytes in the lymph nodes in a region called the ``mantle zone''. "CCL4 was significantly overexpressed in mantle cell lymphomas cells compared with B cells, which may provide growth benefits." (PMID 23946783, 2013).
mastitis (1 paper, 2022). Inflammation of breast tissue during lactation or postpartum due to an obstructed duct or infection. "Besides, CCL3, CCL4, CCL5 and CCL20 have also been reported as differentially expressed in response to mastitis by other investigators." (PMID 36336691, 2022).
measles (1 paper, 2023). A highly contagious viral infection caused by the measles virus. "Transcriptomic analysis of peripheral blood mononuclear cells (PBMCs) from children with measles shows upregulation of mRNAs for IL-1β, CIAS-1/NLRP3, tumor necrosis factor (TNF)α, CCL4/MIP-1β, CXCL2/GRO-β, CXCL8, and TNFAIP3/A20 consistent with NF-κB signaling and inflammasome priming." (PMID 36851476, 2023).
migraine (1 paper, 2021). "The levels of CCL18, CCL22, and CCL4 were different between patients with MD or migraine and controls." (PMID 34575163, 2021). "Levels of IL-1β, CCL3, CCL4, CXCL1, CCL22, and CCL8 were also measured in 55 healthy controls and 64 migraine patients." (PMID 34575163, 2021). "Therefore, we measured the levels of IL-1β, CCL3, CCL4, CXCL1, CCL22, and CCL18 in a cohort of 83 patients with MD, which included 44 EOMD and 39 LOMD, and 64 patients with migraine without vestibular symptoms to control the effect of migraine itself on cytokine levels." (PMID 34575163, 2021).
mycobacterial infection (1 paper, 2022). "Among the molecules, chemokines (CCL3, CCL4, CCL5) and cytokines (IL6, IL1B) are known to induce M1 macrophage polarization in response to mycobacterial infection." (PMID 35821058, 2022).
nephritis (1 paper, 2023). Inflammation of renal tissue. "Consistently, our in vivo data showed that the expression levels of CCL2, CCL3, CCL4, CCL5, CCL19, and CXCL10 increased in the kidney of MRL.Faslpr mice during the development of nephritis." (PMID 37567910, 2023).
neuroblastoma (1 paper, 2025). Neuroblastoma (NB) is the most common solid, extracranial childhood tumor. "High expression levels of CCL2, CCL4, CCL21, CD200, CXCR3, and IGSF6 were significantly associated with improved survival in neuroblastoma patients (all p < 0.001)." (PMID 40718780, 2025). "In our study, we identified four chemokines, CCL2, CCL4, CCL21, and CXCR3, in neuroblastoma samples, which may originate from different cellular subsets." (PMID 40718780, 2025). "Our study demonstrates that tertiary lymphoid structure (TLS)-related genes play a crucial role in neuroblastoma (NB) prognosis, with a 6-gene TLS signature (CCL2, CCL4, CCL21, CD200, CXCR3, and IGSF6) serving as a promising prognostic biomarker for NB." (PMID 40718780, 2025).
neurofibromatosis type 1 (1 paper, 2025). A clinically heterogeneous, neurocutaneous genetic disorder characterized by cafe-au-lait spots, iris Lisch nodules, axillary and inguinal freckling, and multiple neurofibromas. "There exists some evidence that MDK can activate CD8+ T cells to secrete chemokine (C-C motif) ligand 4 (CCL4) in neurofibromatosis type 1 patients via interaction with LRP1 on T cells, but the effect of this interaction on cytotoxicity was not investigated." (PMID 40429950, 2025).
neuropathic pain (1 paper, 2016). Chronic pain caused by damage to nerve fibers. "Of the 47 investigated proteins, 21 (cathepsin S, CCL2, CCL4, CCL16, CFIII, CXCL5, cystatin B, E-Selectin, Fas/TNFRSF6, follistatin, GDF-15, GH, ICAM1, IL8, KLK5, MMP2, MMP9, P-Selectin, sortilin, TIMP4 and VEGF) were detectable by multiplex SP-PLA in ≥ 95% of the neuropathic pain patient samples." (PMID 26914813, 2016).
obliterative bronchiolitis (1 paper, 2016). "The expression of Ccl3, Ccl4, and Il6 were all down-regulated in macrophages exposed to NR58-3.14.3 and are consistent with the down-regulation of Il6 observed in experimental obliterative bronchiolitis following administration of NR58-3.14.3." (PMID 26911327, 2016).
orofacial cleft (1 paper, 2025). A disorder of facial skeleton that is characterized by cleft lip and/or cleft palate that result in feeding, speech and hearing problems caused by failures during development. "There is limited information available on CCL4’s involvement in orofacial cleft morphopathogenesis." (PMID 41226636, 2025).
orthostatic hypotension (1 paper, 2018). Sudden fall of the blood pressure of at least 20/10 mm Hg when a person stands up. "The further observation that down-regulation of CCR5, the cognate receptor for CCL4, causes hypotension is an interesting correlation, since many FM patients report episodes of orthostatic hypotension." (PMID 29927949, 2018).
pancreatic adenocarcinoma (1 paper, 2023). "Notably, CCR5 ligands Ccl3 and Ccl4 are upregulated when DKK1 is expressed and have previously been shown to be strong mediators of Treg infiltration in pancreatic adenocarcinoma." (PMID 35924447, 2023).
parasite (1 paper, 2022). "Though the importance of CCL4 and DDIT4 in immune response has been known, their function in L. crocea is relatively rarely reported, especially after parasite infection." (PMID 35287569, 2022).
parasite infections (1 paper, 2022). "Importantly, we have identified candidate innate immunity-related genes, including CCL4 and DDIT4, that may play key roles in the anti-inflammatory response during parasite infections." (PMID 35287569, 2022).